PODXL (podocalyxin like)
Diseases named in the same sentence as PODXL in open-access papers (continued):
Sharing a sentence is not in itself a finding about the gene and the disease.
pancreatic cancer (19 papers, 2015 to 2025). "High PODXL expression was significantly associated with worse OS and was predictive of shorter OS in multiple cancers, especially pancreatic cancers." (PMID 33088928, 2020). "This integrated approach contributes to a better understanding of how MUC16 and PODXL bind to E-/L-selectins in the presence of hydrodynamic shear, which can lead to improved diagnostic assays and to the prevention of the metastatic spread of pancreatic tumor cells." (PMID 26329844, 2015). "Further investigation is required to determine the specific subtype(s) of pancreatic cancer in which PODXL is expressed." (PMID 40843679, 2025). "High expression of miR-509-3-5p and miR-5100 inhibited the invasion and metastasis of gastric cancers and pancreatic cancers by directly targeting PODXL, functioning as a tumor suppressor." (PMID 32615943, 2020). "Incubation with TGF-β rendered pancreatic cancer cells seemingly more invasive, leading to an increased expression of PODXL, particularly at the invasive front." (PMID 32587323, 2020). "Silencing of PODXL with specific shRNAs markedly reduced the binding of SW1990 pancreatic tumor cells to immobilized E- and L-selectin under physiological flow conditions, indicating a functional role for PODXL in this process." (PMID 32046309, 2020). "Podocalyxin-like protein 1 (PCLP1) binds E- and L-selectin in pancreatic cancer, and is overexpressed in many cancers and on activated platelets." (PMID 28105409, 2016). "MUC16 and PODXL have been identified as functional E- and L-selectins ligands that are overexpressed in metastatic pancreatic cancer cells." (PMID 26329844, 2015). "We recently identified sialofucosylated mucin 16 (MUC16) and podocalyxin (PODXL) as the major functional E- and L-selectin ligands expressed on the surface of metastatic pancreatic cancer cells." (PMID 26329844, 2015). "To validate the measurements obtained using immunopurified MUC16 and PODXL, we also tested E-/L-selectin binding to MUC16-expressing (PODXL-knockdown) and PODXL-expressing (MUC16-knockdown) SW1990 pancreatic cancer cells." (PMID 26329844, 2015). "Furthermore, the heightened miR-5100 expression led to a decrease in the malignant capabilities of pancreatic tumor cells through the inhibition of PODXL." (PMID 39590378, 2024). "Its mechanisms of action and targets may be tissue and disease stage dependent: in pancreatic cancer, it was proposed as anti-metastatic miR, through PODXL silencing." (PMID 34868998, 2021). "The PODXL expression in pancreatic cancer tissues could be analyzed using PcMab-47, and then PODXL-positive patients should be treated using cancer-specific humanized PcMab-60." (PMID 33088928, 2020). "The result of meta-analysis showed that high expressed PODXL was significantly linked with poor OS in pancreatic cancer and glioblastoma multiforme, but not in gastric cancer, esophageal cancer or lung adenocarcinoma." (PMID 32615943, 2020). "In addition to the results found in both cohorts, functional studies were performed in vitro using PANC-1 pancreatic cancer cells either transfected with siRNA against PODXL (siPODXL) or EGFR (siEGFR), or incubated with TGF-β." (PMID 32587323, 2020). "However, in Cohort 2, which comprised only ductal pancreatic cancer, patients with tumors overexpressing both PODXL and EGFR exhibited a significantly shorter overall survival." (PMID 32587323, 2020). "Blockade of PODXL could inhibit GC cell migration and invasion, enforced expression of PODXL did the opposite effect, which were consistent with Taniuchis’ results in pancreatic cancer." (PMID 28432273, 2017). "However, it is undeniable that some others binding sites are existed in 3′UTR of PODXL, For instance, miR-5100, miR-199b-5P are treated as negative regulators of PODXL in pancreatic cancer and acute myeloid leukemia." (PMID 28432273, 2017).
pancreatic cancer (continued). "In another study, sialofucosylated PODXL was demonstrated to be a functional E- and L-selectin ligand expressed by metastatic pancreatic cancer cells in vitro, and was also found to be overexpressed, with membranous localization, in 69 % of 105 pancreatic ductal adenocarcinomas." (PMID 26028992, 2015). "Overexpressed PODXL could be detected in peripheral blood and used as a non-invasive diagnostic biomarker for the detection of pancreatic cancer." (PMID 32615943, 2020). "Previous studies have demonstrated PODXL to be a functional ligand of E- and L- selectins in pancreatic cancer suggesting that its expression may promote haemotogenic spread of metastases by facilitating binding of circulating tumour cells to selectin-expressing host cells." (PMID 26028992, 2015). "Whether PODXL is a marker of poor prognosis also in pancreatic cancer, remains unclear." (PMID 26053486, 2015). "In flow cytometry, PcMab-60 reacted with the PODXL-overexpressed LN229 and pancreatic cancer MIA PaCa-2." (PMID 40843679, 2025). "The upregulation of PODXL and ITGB1 in surgically resected pancreatic cancer tissues is correlated with an unfavorable postoperative prognosis." (PMID 35275973, 2022). "Immunohistochemistry was performed using anti-PODXL and anti-ITGB1 antibodies on 24 pancreatic cancer tissue samples preoperatively obtained by endoscopic ultrasound-guided fine-needle aspiration biopsy." (PMID 35275973, 2022). "The effect of TGF-β-induced expression and siRNA-mediated knockdown of PODXL and EGFR, were investigated in pancreatic cancer cells (PANC-1) in vitro." (PMID 32587323, 2020). "This study thus aimed to investigate the relationship between the expression of PODXL and EGFR in periampullary adenocarcinomas, including pancreatic cancer, with focus on morphological subtypes." (PMID 32587323, 2020). "We also examined the functional interplay between PODXL and EGFR in pancreatic cancer cells in vitro." (PMID 32587323, 2020). "This study showed that the direct interaction of PODXL with the large GTP-ase dynamin-2 regulates cytoskeleton dynamics, promoting migration and metastasis of pancreatic cancer cells." (PMID 32046309, 2020). "We previously reported that overexpression of PODXL, BCL7B, and ARHGEF4 in pancreatic cancer tissue is correlated with pancreatic cancer-related survival." (PMID 31166991, 2019). "Furthermore, the direct influence of miR-5100 on the PODXL gene via binding to the 3’UTR has been shown to reduce migration, invasion, and colony formation in pancreatic cancer." (PMID 38879474, 2024). "The aim of this study was to investigate whether PODXL and ITGB1 are useful preoperative markers for the prognosis of postoperative pancreatic cancer patients in comparison with the TNM staging system." (PMID 35275973, 2022). "PODXL is overexpressed by metastatic pancreatic cancer cell lines (Pa03C, Pa07C, and SW1990) but not by nonmalignant pancreatic counterparts." (PMID 34201212, 2021). "Specifically, the high expressed PODXL was correlated with poor prognosis significantly in the glioblastoma multiforme and pancreatic cancer, but not in the esophageal adenocarcinoma, gastric cancer and lung adenocarcinoma." (PMID 32615943, 2020). "The aim of this study was to investigate the use of PODXL, BCL7B, ARHGEF4, and the integrin family member ITGB1 as useful markers for the prognosis of postoperative pancreatic cancer patients in comparison with tumor size and the tumor node metastasis (TNM) staging system." (PMID 31166991, 2019). "Therefore, upregulation of PODXL and ITGB1 may indicate preoperative neoadjuvant therapy for pancreatic cancer patients by accurately predicting the postoperative prognosis." (PMID 35275973, 2022). "Furthermore, silencing PODXL in pancreatic cancer cells resulted in the down-regulation of EGFR, but not vice versa." (PMID 32587323, 2020).
pancreatic cancer (continued). "The association between the overexpression of PODXL and EGFR seen in I-type periampullary tumors was not confirmed in PB-type tumors or in pancreatic cancer in Cohort 2 in the Cox regression analysis, further indicating that I-type tumors resemble and should be treated as colorectal cancer." (PMID 32587323, 2020). "Unfortunately, we herein could not analyze PODXL expression in pancreatic cancer tissues because PcMab-60 was not useful for immunohistochemical analysis." (PMID 33088928, 2020). "It is notable that the combination of PODXL with ITGB1 and the combination of BCL7B with ITGB1 accurately predicted the postoperative outcomes of pancreatic cancer patients with or without adjuvant therapies." (PMID 31166991, 2019).
glioblastoma (18 papers, 2009 to 2025). The most malignant astrocytic tumor (WHO grade IV). "And among the 31 types of cancers, 9040 patients, the significant association between high expressed PODXL and poor OS was found in 3 types of cancers, including the glioblastoma multiforme, kidney renal papillary cell carcinoma and pancreatic adenocarcinoma." (PMID 32615943, 2020). "A recent study reported that PODXL expression was detected on the surface of 42.9% of anaplastic astrocytoma samples and 54.8% of glioblastoma samples, suggesting that PODXL may be associated with the malignant progression of astrocytic tumors." (PMID 23596468, 2013). "Our group previously generated a CasMab against PODXL, designated PcMab-60 (IgM, κ), by immunizing mice with soluble PODXL expressed in LN229 glioblastoma cells." (PMID 40843679, 2025). "Using recombinant PODXL derived from glioblastoma LN229 as an antigen, we developed more than one hundred clones of anti-PODXL mAbs." (PMID 38203331, 2023). "Here, we developed an anti-PODXL cancer-specific mAb (CasMab), PcMab-6 (IgG1, kappa), by immunizing mice with a soluble PODXL ectodomain derived from a glioblastoma LN229 cell." (PMID 38203331, 2023). "Among the fourteen A-to-I non-synonymous editing events, three ones have been experimentally dissected as pivotal modulators involving in tumorigenesis, including A1099G at AZIN1 in HCC, A725G at NEIL1 in glioblastoma and A722G at PODXL in gastric cancer." (PMID 36476255, 2022). "A joint result of our meta-analysis and TCGA datasets validation identified the correlation between the expression level of PODXL and the glioblastoma multiforme, pancreatic adenocarcinoma, esophagus cancer, gastric cancer and lung adenocarcinoma." (PMID 32615943, 2020). "As a positive control, we used PcMab-47, which strongly reacted with endogenous PODXL of LN229 glioblastoma cell line (left)." (PMID 33088928, 2020). "In SW1783 and U-87 astrocytoma cell lines, PODXL increased cell survival against apoptosis induced by temozolomide, a DNA-alkylating agent widely used as standard therapy for glioblastoma multiforme, through the up-regulation of PI3K/AKT signaling pathway." (PMID 32046309, 2020). "And it is reported that high PODXL expression is related to increasing glioma grade and decreased survival time in patients with glioblastoma multiforme." (PMID 29322932, 2017). "PODXL is nonetheless significantly overexpressed in glioblastoma, suggesting a possible implication in tumor angiogenesis." (PMID 19924294, 2009). "A role for PODXL in tumor cell proliferation was first evidenced in JHU-0879 glioblastoma multiforme stem-like cell line after silencing of PODXL with specific short hairpin RNAs (shRNAs), which resulted in a significant reduction in cell proliferation and oncosphere formation." (PMID 32046309, 2020). "In addition, it was demonstrated that high PODXL expression correlates with increasing glioma grade and is a marker of poor outcome in patients with glioblastoma multiforme." (PMID 30867054, 2019). "Our results showed that PODXL knockdown significantly increased cell apoptosis in the presence of temozolamide, suggesting that PODXL may be a potential target for overcoming chemoresistance in astrocytomas, particularly, glioblastomas." (PMID 23596468, 2013). "The involvement of PODXL in glioblastoma multiforme (GBM) stem-like cell proliferation was demonstrated with PODXL positive cell populations in two GBM oncosphere lines that exhibited significantly elevated growth compared with PODXL negative cells." (PMID 31083655, 2019). "In this study, we developed an anti-PODXL cancer-specific mAb (CasMab), named as PcMab-60 (IgM, kappa) by immunizing mice with soluble PODXL, which is overexpressed in LN229 glioblastoma cells." (PMID 33088928, 2020). "Herein, we immunized mice with recombinant human PODXL, which was produced using LN229 glioblastoma cells." (PMID 28384052, 2017).
glioblastoma (continued). "A novel anti-PODXL mAb, PcMab-6 (IgG1, kappa), reacted with endogenous PODXL on a glioblastoma LN229 cell line but not with PODXL-KO LN229 (PDIS-13)." (PMID 38203331, 2023).
gastric cancer (17 papers, 2015 to 2025). A primary or metastatic malignant neoplasm involving the stomach. "Future studies should confirm this association and resolve the mechanisms by which PODXL affects the development and behavior of gastric cancer." (PMID 26674770, 2015). "Increasing evidence has proven that ADAR2 can block CSC proliferation by inactivating podocalyxin-like (PODXL) in gastric cancer and inhibiting COPA (coatomer protein complex, subunit α) in HCC." (PMID 37853437, 2023). "In gastric cancer, ADAR2-induced editing of the podocalyxin-like (PODXL) gene confers a loss-of- function phenotype that neutralizes the tumorigenic ability of unedited PODXL69." (PMID 32346127, 2020). "In SGC-7901 and AGS gastric cancer cells, silencing of PODXL impaired liver metastasis in nude mice." (PMID 32046309, 2020). "KLF4, a member of the KLF family of zinc finger transcription factors that regulates cell proliferation, differentiation, and survival, represses PODXL expression in human gastric cancer cells by directly binding to the 5 ́UTR of PODXL." (PMID 32046309, 2020). "Gastric cancer progression is significantly increased upon PODXL expression, a phenotype reduced by concomitant RUFY1 silencing." (PMID 32850870, 2020). "The expression levels of miR-509-3 were lower in multiple cancers, and miR-509-3-5P downregulation promoted the migration and invasion of gastric cancer cells by targeting PODXL." (PMID 29740512, 2018). "Overexpression of miR-509-3-5P inhibits the invasion and metastasis of gastric cancer in vitro and in vivo, functioning as a tumor suppressor, by targeting PODXL." (PMID 28432273, 2017). "This is the first report on the prognostic role of PODXL in esophageal adenocarcinoma and validates recent findings in gastric cancer." (PMID 27478410, 2016). "In gastric cancer, PODXL expression by the polyclonal antibody HPA2110 is an independent marker of poor prognosis." (PMID 26674770, 2015). "The aim of this study was to investigate PODXL expression in gastric cancer to reveal its possible role in aggressiveness and prognosis." (PMID 26674770, 2015). "This is, to our knowledge, the first report on the prognostic value of PODXL expression in gastric cancer." (PMID 26674770, 2015). "The frequency of PODXL positivity in gastric cancer was close to that seen in breast and ovarian cancer (40% and 67%)." (PMID 26674770, 2015). "In conclusion, PODXL immunostaining serves as an independent marker of poor prognosis in gastric cancer." (PMID 26674770, 2015). "PODXL positivity by the polyclonal antibody indicated reduced gastric-cancer-specific 5-year survival of 24.0% (95% CI 16.9–31.1), compared to 43.3% (95% CI 33.7–52.9) for patients with PODXL negativity (p = 0.001)." (PMID 26674770, 2015). "The aim of this study was to investigate PODXL expression in gastric cancer by use of two different antibodies." (PMID 26674770, 2015). "Targeting PODXL/RUFY1 complex may improve the prognosis of gastric cancer (GC) and provide new treatment opportunities for GC patients." (PMID 33042807, 2020). "The contribution of PODXL to gastric cancer proliferation has been demonstrated in several studies." (PMID 32046309, 2020). "Similarly, PODXL silencing in HCT15 colon cancer cells and in SGC-7901 and AGS gastric cancer cells led to a reduction of EMT-associated markers." (PMID 32046309, 2020). "In BGC823 and MGC803 gastric cancer cells, PODXL promoted colony formation." (PMID 32046309, 2020). "Our study aimed to investigate the clinicopathological feature and prognostic role of miR-509-3-5P in gastric cancer, to determine the invasive and metastatic role of miR-509-3-5P in vitro and in vivo and to explore the molecular mechanism between miR-509-3-5P and PODXL." (PMID 28432273, 2017). "The aim of our study was to investigate the clinical significance, biological function and molecular mechanism of PODXL in gastric cancer (GC)." (PMID 29748877, 2019).
gastric cancer (continued). "Similar findings have been made in gastric cancer (GC) cells, in which in vitro studies show significantly inhibited tumour growth and reduced liver metastasis in transfected mice, suggesting a functional role of PODXL in cancer metastasis." (PMID 34201212, 2021). "In gastric cancer, ADAR2-induced recoded podocalyxin-like (PODXL) (histidine-to-arginine substitution at residue 241) protein was found to suppress tumorigenesis by neutralizing the tumorigenic capacity of wild-type PODXL." (PMID 39126156, 2025). "PODXL in SGC-7901 and AGS gastric cancer cells also enhanced primary tumor growth in nude mice." (PMID 32046309, 2020). "Negative PODXL expression was denoted in 14.2 % of the esophageal cancers and in 21.5 % of the gastric cancers, but the difference between locations was not statistically significant." (PMID 27478410, 2016). "Here we did not study PODXL expression in lymph node metastases in gastric cancer, and none of the patients in this cohort received preoperative chemotherapy, although it is currently rather routine." (PMID 26674770, 2015). "Basically PODXL is a transmembrane molecule, and therefore it was surprising not to find it on cell membranes in gastric cancer cells by either antibody." (PMID 26674770, 2015).